PDHB (pyruvate dehydrogenase E1 subunit beta)
Diseases named in the same sentence as PDHB in open-access papers (continued):
Sharing a sentence is not in itself a finding about the gene and the disease.
Alzheimer disease (1 paper, 2023). A progressive, neurodegenerative disease characterized by loss of function and death of nerve cells in several areas of the brain leading to loss of cognitive function such as memory and language. "KEGG pathway enrichment analysis revealed that PDHB expression may be associated with multiple pathways, including oxidative phosphorylation, Parkinson disease, ribosome and Alzheimer disease, among others." (PMID 37641032, 2023).
breast tumors (1 paper, 2022). "Among them, the expression of the majority of genes was decreased in tumor samples except for four genes (ATP7B, SLC31A1, PDHB and CDKN2A), suggesting cuproptosis signaling was significantly downregulated in breast tumors." (PMID 36497253, 2022).
Cerebral ischemia (1 paper, 2024). Restriction of arterial blood supply to the brain associated with insufficient oxygenation to support the metabolic requirements of the tissue. "The present study also reported the involvement of PDHB in the cuproptosis pathway in cerebral ischemia." (PMID 39360273, 2024). "Eight hub genes (FDX1, LIPT1, LIAS, DLD, PDHA1, DLAT, PDHB, and GLS) were identified as potential core targets of cerebral ischemia." (PMID 39360273, 2024).
Cluster headache (1 paper, 2019). A type of headache characterized by repeated attacks of unilateral pain lasting 15 to 180 minutes and associated with local autonomic signs. "Also, we determined that TBP, IPO8 and PDHB were suitable reference genes in cluster headache fibroblasts." (PMID 31366133, 2019).
coronary heart disease (1 paper, 2022). "The results showed that six CRGs (LIAS, LIPT1, DLAT, PDHB, MTF1, and GLS) were markedly differentially expressed between stable coronary heart disease (stable_CAD) and AMI." (PMID 36440046, 2022).
COVID-19 (1 paper, 2023). A disease caused by infection with severe acute respiratory syndrome coronavirus 2. "And the results of proteomics showed that the expression levels of PDHA1 and PDHB were significantly increased in COVID-19 patient samples." (PMID 37533853, 2023). "In COVID-19 samples, the expression of PDHA1 was significantly higher compared to control samples, while the difference in PDHB expression between COVID-19 and control samples was not statistically significant." (PMID 37533853, 2023).
cyst (1 paper, 2015). A sac-like closed membranous structure that may be empty or contain fluid or amorphous material. "The few notable changes in expression include an operon coding for pyruvate dehydrogenase genes involved in the TCA cycle (pdhA, pdhB, pdhC and pdhD) that increased 6-fold in 72 hours and 96 hours of cyst development." (PMID 25758168, 2015).
diabetes (1 paper, 2024). "PDHB has garnered widespread attention as a novel diabetes risk gene, but further research is still needed to elucidate its role in diabetes." (PMID 38904034, 2024). "In conclusion, there is a growing recognition of the impact of PDC and its constituent components, DLAT, DLD, PDHA1, and PDHB, on diabetes." (PMID 38904034, 2024).
diffuse large B-cell lymphoma (1 paper, 2022). "However, a large majority of cuproptosis-associated genes including FDX1, LIAS, LIPT1, DLD, DLAT, and PDHB acted as a low-risk indicator in Lymphoid neoplasm diffuse large B-cell lymphoma (DLBC)." (PMID 36105090, 2022).
Dilater cardiomyopathy (1 paper, 2024). "The remaining pathways were all detected with a predominance of control proteins, such as the Citrate cycle (TCA cycle) (P-value < 0.0001; ACLY, DLST, PDHA1, PDHB), except Dilater cardiomyopathy (DCM) (P-value = 0.0006; ACTB, ADCY8, LOC396781, TPM1)." (PMID 38409238, 2024).
lactic acidosis (1 paper, 2025). Metabolic acidosis characterized by the accumulation of lactate in the body. "Pyruvate dehydrogenase (PDH) deficiency is an uncommon condition responsible for primary refractory lactic acidosis, and PDH E1β (PDHB) subunit gene mutation rarely causes of PDH deficiency." (PMID 40050878, 2025).
mastitis (1 paper, 2021). Inflammation of breast tissue during lactation or postpartum due to an obstructed duct or infection. "Although such a role in staphylococci was not confirmed experimentally, PdhB was reported as the only cellular protein belonging to the core exoproteome of the bovine S. aureus mastitis isolates." (PMID 34070083, 2021).
mesothelioma (1 paper, 2022). A usually malignant and aggressive neoplasm of the mesothelium which is often associated with exposure to asbestos. "Similarly, cuproptosis-associated genes including LIAS, LIPT1, PDHB, GLS, and CDKN2A had significant overall survival in Mesothelioma (MESO) (p < 0.05)." (PMID 36105090, 2022).
non-alcoholic fatty liver disease (1 paper, 2024). "Currently, research is primarily focusing on the role of PDHB in cancer, particularly in the cuproptosis pathway associated with non-alcoholic fatty liver disease (NAFLD), where both DLD and PDHB are potential candidate genes for NAFLD diagnosis and treatment options." (PMID 39360273, 2024).
non-small cell lung carcinoma (1 paper, 2022). A group of at least three distinct histological types of lung cancer, including non-small cell squamous cell carcinoma, adenocarcinoma, and large cell carcinoma. "Specifically, PDHB was frequently Del in LUSC and was related to worse OS in non-small cell lung cancer, which agrees with the past result." (PMID 36209249, 2022).
Obesity (1 paper, 2020). Accumulation of substantial excess body fat. "A selective knockdown of ABHD6 protects mice from high-fat-induced obesity, while PDHB on chromosome 13 has been described in cattle and pigs and is a candidate gene for intramuscular fat deposition." (PMID 32660013, 2020).
pulmonary fibrosis (1 paper, 2023). Chronic progressive interstitial lung disorder characterized by the replacement of the lung tissue by connective tissue, leading to progressive dyspnea, respiratory failure, or right heart failure. "It’s reported that the CRGs, such as FDX1, LIAS, DLD, PDHA1, PDHB, DLAT, and LIPT1, were down-regulated in the lung tissues of pulmonary fibrosis mouse model, and the same results were obtained via analysis of lung tissues scRNA-seq data for human pulmonary fibrosis." (PMID 37266442, 2023).
scleroderma (1 paper, 2023). Scleroderma is a rare autoimmune connective tissue disorder characterized by abnormal hardening of the skin and, sometimes, other organs. "In addition, eSNPs affecting PDHB expression colocalize with scleroderma risk alleles (PP.H4 = 0.992)." (PMID 37805522, 2023). "Similarly, we observed colocalization at the PDHB gene with scleroderma." (PMID 37805522, 2023).
tumor (60 papers, 2018 to 2026). "High PDHB expression is significantly associated with high HCC tumour stage and grade and poor patient prognosis." (PMID 40809021, 2025). "The genes LIPT1, PDHA1, and PDHB are responsible for encoding the lipoic acid pathway, which has been found to have significant implications in tumor progression." (PMID 38114959, 2023). "Our findings suggest that decreased expression of PDHB is closely associated with an elevated risk of tumor progression in ccRCC." (PMID 37641032, 2023). "The dysregulation of PDHB in ccRCC was associated with survival outcomes, pathway activation and immune infiltration among tumor microenvironments." (PMID 37350959, 2023). "Furthermore, cuproptosis-related gene PDHB might inhibit the progression of ccRCC by mediating immune-active tumor microenvironment associated with cell death and immune responses." (PMID 37350959, 2023). "A novel prognostic risk model based on four CRGs (ORC1, PTTG1, DLAT, PDHB) was developed to stratify COAD patients into high-risk and low-risk groups, assessing overall survival, tumor microenvironment, and mutational landscape differences." (PMID 40276654, 2025). "In the GPL570 dataset, upregulation of LIPT1, FDX1, LIAS, DLAT, DLD, and PDHB was noted in tumor samples, while MTF1 was downregulated." (PMID 40410601, 2025). "When dataset was expanded with GTEx data, a similar pattern was observed for most genes, although LIAS, PDHA1, and PDHB showed downregulation in tumor tissues." (PMID 40410601, 2025). "Studies have shown that PDHB activity accelerates tumor cell growth, and overexpression of PDHB can inhibit tumor cell migration and growth by suppressing the signaling pathway." (PMID 39482784, 2024). "Specifically, genes such as LIPT1, ATP7A, LIAS, DBT, and PDHB were found to be significantly downregulated in the tumor tissue." (PMID 38898987, 2024). "PDHB expression was significantly lower in ccRCC tumor tissues compared with normal kidney tissues both in TCGA-ccRCC and TCGA+GTEx ccRCC cohorts (P<0.001)." (PMID 37350959, 2023). "Thioctyl has the ability to target DLAT, PDHA1, and PDHB, which in turn can modulate tumor progression by influencing diverse metabolic pathways." (PMID 38114959, 2023). "Out of the identified regulators, six genes (SLC6A3, MITD1, CCS, LIPT2, ATOX1, and GLS) showed increased expression in tumor tissues, while PDHB had higher expression in normal tissues." (PMID 38159255, 2023). "In contrast, the expression levels of the pro-cuproptosis genes DLAT and PDHB were obviously reduced in tumor tissues as compared to normal tissues." (PMID 36947706, 2023). "Ultimately, in vivo experiment confirmed that knocking down PDHB dramatically accelerated tumor growth." (PMID 37350959, 2023). "The genes PDHA1 and PDHB, both part of the pyruvate dehydrogenase complex, are reported to influence oxidative phosphorylation, tumor growth, metastasis, and glycolysis regulation." (PMID 37239150, 2023). "Of note, seven out of ten pivotal CRGs, which were identified in Science article, showed significantly altered expression patterns, with CDKN2A exhibited higher and DLAT, DLD, FDX1, LIAS, MTF1, PDHB exhibited lower expression in tumor tissues (P<0.05)." (PMID 37384293, 2023). "Ultimately, we analyzed the correlation between immune characteristics among tumor microenvironment and PDHB expression level." (PMID 37350959, 2023). "Above results suggested that low expression of PDHB plays a vital role in regulating suppressive tumor immune microenvironment mainly via up-regulating Treg cells by ssGSEA and CIBERSOFT algorithms." (PMID 37350959, 2023). "Pan-cancer detection of PDHB expression showed that PDHB expression in tumor tissues was lower than that in normal tissues, including ACC, BLCA, ESCA, HNSC, LUSC and STAD." (PMID 37641032, 2023). "The dysregulation of PDHB in ccRCC was characterized, together with survival outcomes, pathway enrichment and immune infiltration among tumor microenvironments." (PMID 37350959, 2023).
tumor (continued). "MiR-203, miR-146b-5p, and miR-363-3p promote pro-tumor cell growth, invasion, inhibition of apoptosis, and enhancement of glycolysis by targeting PDHB." (PMID 35990673, 2022). "A heatmap showed that the levels of expression of ATP7B, DLAT, DLD, LIAS, and SLC31A1 were upregulated and the levels of expression of DBT, FDX1, and PDHB downregulated in tumor samples." (PMID 36092880, 2022). "Tumor suppressor miRNAs, including the let-7 and miR-26 family members were found to be prominent in the regulation of PDHB." (PMID 34827193, 2021). "Downregulation of PDHB allows cancer cells to maintain active proliferative status by enhancing cytosolic glycolysis and lactate production in the surrounding tumor microenvironment." (PMID 32850313, 2020). "The results suggested that tumor immune escape and antitumor immunity might be involved in the oncogenic process of PDHB-mediated ccRCC." (PMID 37641032, 2023). "The expression level of PDHB was lower in tumor tissue compared with normal tissue." (PMID 37641032, 2023). "We used data from TCGA and GEO to assess the expression of PDHB in normal and tumor tissues." (PMID 37641032, 2023). "It was unclear whether PDHB could affect the aggregation of immune cells in the tumor microenvironment to influence the prognosis of ccRCC." (PMID 37641032, 2023). "PDHB could act as regulatory targets of multiple non-coding RNAs to regulate tumor cell progression." (PMID 36211401, 2022). "The PDHB gene could be a potential molecular biomarker for predicting tumour immune response." (PMID 38495196, 2024). "FDX1, LIAS, LIPTQ, SLC31A1, and PDHB showed no mutation in LUAD tumor tissues." (PMID 36983664, 2023). "In addition, PDHB has also been studied in various tumor cells." (PMID 35990673, 2022). "Moreover, we explored the potential prognostic value of PDHB using Kaplan Meier plotter and found that high PDHB expression correlated with poor relapse-free survival for patients with LumA, LumB and Basal tumor subtypes." (PMID 29940887, 2018). "The convergence of tumor suppression (FHIT, FAM107A), metabolic reprogramming (PDHB), and immune/signaling (PTPRG, FAM3D) genes within a single genomic region suggests a potential resistance-associated haplotype block." (PMID 42302616, 2026). "Pyruvate dehydrogenase E1 subunit beta (PDHE1-B), 2-oxoglutarate dehydrogenase E1 (OGDH-E1), and cytochrome c oxidase subunit 2 were less-abundant proteins in the S tumor samples." (PMID 39195201, 2024). "Specifically, the expression levels of SLC6A3, MITD1, and PDHA1 exhibited an increasing trend with tumor pathological stage, whereas CCS, LIPT2, PDHB, and PDHA1 displayed a decreasing trend in response to radiation therapy." (PMID 38159255, 2023). "The methylation levels of LIAS, PDHB, and LIPT1 in the PDAC tumor tissues were significantly different from those in the normal tissues (FDR < 0.05)." (PMID 36826087, 2023). "In tumor tissues, the abundance of CDKN2A and MTF1 were higher, as well as the levels of DLD, FDX1, GLS, LIPT1 and PDHB were down-regulated." (PMID 37662947, 2023). "The results show a significant increase in the expression of SLC3A3, MITD1, LIPT2, ATOX1, PDHB, and GLS in tumor tissues compared to normal esophageal tissues." (PMID 38159255, 2023). "We found that LIAS and CDKN2A were significantly upregulated in tumor samples, and FDX1, DLD, DLAT, PDHA1, PDHB, MTF1, and GLS were significantly downregulated in tumor samples." (PMID 36531222, 2022). "In tumor cell-enriched region, the expression of COPS5, DLAT, DLD, FDX1, NFE2L2, PDHA1 and PDHB in the high score group is higher than that in the low score group, while the opposite is true for DLST, GCSH and LIPT2 (P <0.05)." (PMID 36618352, 2022). "The heatmap showed that these genes were upregulated in tumor tissue The interaction network involving these genes indicated that DLD, DLAT, and PDHB were the hub genes." (PMID 36386799, 2022).
tumor (continued). "The expression of MTF1, NLRP3, and SLC31A1 was positively related with ImmuneScore, StromalScore, and ESTIMATEScore in almost all types of tumor, whereas ATP7B, DLAT, DLD, LIAS, PDHA1, and PDHB were significantly negatively correlated with the scores." (PMID 36387247, 2022). "First, from the aspect of expression levels and copy number variation, we speculated that PDHB, FDX1, and DLD were significantly differentially expressed in BLCA with diagnostic efficacy because the AUCs of them were more than 0.7 to differentiate tumor and normal tissue." (PMID 36506302, 2022). "Among them, 7 genes (DLAT, DLD, GCSH, LIAS, LIPT1, PDHA1, and PDHB) were upmodulated, whereas 3 genes (ATP7B, FDX1, and SLC31A1) were downmodulated in the tumor group in contrast with the normal group (p < 0.05)." (PMID 36046242, 2022). "Subsequently, we detected the expression of these CRGs in tumor and normal samples and found that 6 genes, FDX1, LIAS, DLD, DLAT, PDHB and MTF1, were significantly downregulated in tumors, while 2 genes, GLS and CDKN2A, were significantly upregulated." (PMID 36246586, 2022). "GEGFR, CD40, SPATA2, ZBP1, ID1, and MYC showed a significant CNV amplification in most tumour types; however, TLR3, PDHB, FAS, and MAP3K showed a significant CNV deletion in most tumour types." (PMID 36186436, 2022). "This called for more practical testing, so in the Taizhou cohort, we performed qRT-PCR experiments on 127 tumor tissues and their corresponding normal samples to obtain the expression of genes (FDX1, LIAS, PDHB, and MTF1)." (PMID 36212447, 2022). "Moreover, we checked the mRNA expression of PDHB in GEO and ICGC datasets and found that GSE76351 and GSE6841 revealed decreased expression level of PDHB in tumor tissues." (PMID 37641032, 2023). "Interestingly, MTF1, PDHB and GLS were reported to be highly expressed in other tumor types, while in our study, we found that these genes were strongly associated with good prognosis." (PMID 36620594, 2022). "In the Human Protein Atlas database, the expressions of GLS, MTF1 and PDHA1 in tumor tissues were lower compared with those in normal tissues, while the expressions of DLAT and PDHB were significantly higher in tumor tissues compared with those in normal tissues." (PMID 36620594, 2022). "Levels of expression of the ATP7B, DLAT, and LIAS proteins were higher, whereas the levels of expression of DBT and PDHB were lower, in tumor samples than in non-tumorous kidney tissue, in accordance with the results of differential mRNA analysis." (PMID 36092880, 2022). "Jab1 expression is positively correlated with PDHB (R = 0.37, P = 0.019), DLD (R = 0.37, P = 0.02) and SLC31A1 (R = 0.23, P = 0.15) expression while negatively correlates with DLST (R = -0.32, P = 0.047) expression in tumor cell-enriched region." (PMID 36618352, 2022). "PDHB also inhibits RasV12-driven ERK signaling and tumor cell proliferation." (PMID 35990673, 2022). "Moreover, further analysis was made to investigate the mRNA expression level of CRGs between normal and CRC samples, and we found that the expressions of FDX1, DLD, DLAT, PDHB, and MTF1 were significantly decreased, whereas LIPT1, GLS, and CDKN2A were significantly upregulated in tumor samples." (PMID 37006250, 2023). "We found that FDX1, LIPT1, DLAT, PDHA1, PDHB, DLST, and ATP7A were significantly differentially expressed in tumor and nontumor tissues, with the standard of p < 0.05." (PMID 36975441, 2023).